KRAS (KRas proto-oncogene, GTPase)
Diseases named in the same sentence as KRAS in open-access papers (continued):
Sharing a sentence is not in itself a finding about the gene and the disease.
cancer (continued). "Mutated RAS genes, such as HRAS, NRAS, and KRAS, have also been observed in 10–30% of human cancers." (PMID 36421339, 2022). "In the current study, we observed distinct patterns in KRAS mutations where the position and type of substitution varied between different cancers." (PMID 35319967, 2022). "KRAS is the most frequently mutated proto-oncogene in human cancer, yet despite success targeting the G12C allele, targeted therapy for other hotspot mutants of KRAS has not been described." (PMID 35864332, 2022). "In fact, decreased OXPHOS, elevated glycolysis, and increased generation of reactive oxygen species have been observed as the main features in the cancer cells with oncogenic mutations of KRAS." (PMID 36613455, 2022). "Activating rat sarcoma vial oncogene (RAS) mutations, including KRAS, are the most commonly mutated oncogenes in all cancers, although they are unevenly distributed among different types of cancers." (PMID 35681599, 2022). "RAS is the most frequently mutated oncogene in cancer, and it includes KRAS, HRAS, and NRAS subtypes of which KRAS is commonly seen in cancer." (PMID 35685832, 2022). "Several reports revealed that acquisition of Kirsten rat sarcoma 2 viral oncogene homolog (KRAS) mutations in CRC play significant roles in cancer progression." (PMID 35203586, 2022). "Our research suggested that KRAS was associated with immunotherapeutic effects and cell viability in multiple tumors and had excellent potential as a cancer-targeted drug." (PMID 36330448, 2022). "Previous studies have shown that cancer cells with KRAS mutations exhibit rewired glucose metabolism and higher levels of GLUT1 expression." (PMID 36619305, 2022). "In this experiment, rat sarcoma (RAS) is the most regularly mutated oncogene in cancer, with Kirsten rat sarcoma (KRAS) becoming the most frequently mutated RAS isoform, accounting for over 80% of RAS mutations observed in human cancer." (PMID 36091786, 2022). "In a cancer setting, the autophagy–lysosome system is crucial for the survival and dissemination of KRAS-mutated adenocarcinomas, which are characterized by the ability to grow in nutrient- and oxygen-deficient environments." (PMID 36601538, 2022). "KRAS mutation occurs in nearly 30% of human cancers, yet the most prevalent and oncogenic KRAS(G12D) variant still lacks inhibitors." (PMID 35075146, 2022). "While KRAS1 is a pseudogene, mutation of KRAS2 (commonly known as KRAS oncogene) is directly or indirectly associated with human cancers." (PMID 35409064, 2022). "The G12D-9mer and G12D-10mer are considered public or shared neoantigens due to the high frequency of cancers with KRAS-G12D mutations." (PMID 35587797, 2022). "While this cancer has shown remarkable therapy resistance, new approaches to inhibit mutated KRAS, KRAS activators and effectors show promise in breaking this therapeutic deadlock." (PMID 36579598, 2022). "Overall, KRAS accounts for 85% of RAS mutations observed in human cancers, and KRAS(G12C) mutation occurs in 13% of NSCLCs." (PMID 36499382, 2022). "KRAS G13 mutations have also been identified in cancers and have been potential therapeutic targets for epidermal growth factor receptor (EGFR) inhibitors." (PMID 36497424, 2022). "The KRASG12C mutation accounts for approximately 12% of KRAS mutations across all human cancers and is the predominant mutation in KRAS-mutant non–small cell lung adenocarcinomas." (PMID 35753348, 2022). "A greater understanding of the mutational landscape of these cancers and how it influences response to direct KRAS G12C inhibitors will help enrich treatment populations and widen the therapeutic window." (PMID 36284306, 2022). "Despite being the most frequently mutated oncogene in human cancers, therapeutic targeting of KRAS-driven tumors remains a formidable challenge." (PMID 35319967, 2022).
cancer (continued). "KRAS mutations have been discovered in multiple cancer types, including NSCLC, and are related to cancer metabolism reprogramming (e.g., promotion of glutaminolysis and glycolysis)." (PMID 36532721, 2022). "Since siRNA has the ability to reduce the expression of target genes, studies have focused on using siRNA to down-regulate cancer-associated genes, including undruggable genes (e.g., KRAS, MYC)." (PMID 36015212, 2022). "Taken together, these results suggest that the extracellular lipid depletion reduces cell proliferation in all KRAS mutant cancer cell lines, while causing only a moderate increase in cell death in PDAC cells." (PMID 34998392, 2022). "Due to the high relevance and frequency of KRAS mutations in other cancers, especially lung cancers, early studies sought to detect these in MPM, utilizing targeted approaches." (PMID 36077838, 2022). "For this reason, we need to search and find cancer patients with this mutation and we need sensitive and accurate methods for detecting KRAS in cfDNA." (PMID 36386815, 2022). "We next studied mutations to known cancer genes such as KRAS, and reveal concerted patterns of metabolic changes associated with mutation." (PMID 36321551, 2022). "Metabolic pathways associated with KRAS mutations include aminoacyl‐tRNA biosynthesis, amino acid metabolism and notably a pathway suspected to be essential for cancer survival: glutamine and glutamate metabolism." (PMID 36321551, 2022). "But, until recently, inhibiting KRAS, the most frequent target of oncogenic mutations found in about 15% of all cancer patients and 33% of those with lung adenocarcinoma, has been notoriously difficult." (PMID 35857848, 2022). "KRAS mutations account for the most frequent mutations in human cancers, and are generally correlated with disease aggressiveness, poor prognosis, and poor response to therapies." (PMID 35158933, 2022). "The 8th AJCC Cancer Staging Manual specifies that the level of evidence for KRAS mutation as a prognostic and predictive factor is grade I and II, respectively." (PMID 36544770, 2022). "KRAS is justifiably renowned as one of the most highly mutated oncogenes in human cancers and implicated in poor survival, particularly in pancreatic (~95%), colorectal (~41%), and lung (~32%) cancers." (PMID 36224201, 2022). "We next evaluated PEAK2 cancer activity by transducing a rat PEAK2 expression construct (named PEAK2Myc) in KRAS-mutated HCT116 CRC cells that expressed low endogenous PEAK2." (PMID 35740644, 2022). "Starting from these assumptions in this study, we evaluated the incidence of CHIP in the analysis of KRAS mutations in the routine diagnostic cfDNA testing in patients with advanced cancer." (PMID 36010306, 2022). "More than half of these mutations were common cancer driver mutations, including canonical mutations in KRAS and PIK3CA." (PMID 36311816, 2022). "Recent advances in cancer metabolism research have suggested that metabolic changes caused by RAS mutations are potential therapeutic targets in KRAS-mutated CRC patients." (PMID 36291140, 2022). "An ongoing phase II trial indicated that CD8+ cells with targeting KRAS mutation showed effective treatment against cancer with mutant KRAS G12D." (PMID 35810469, 2022). "In particular, increased ROS production, which has been shown to be functionally required for KRAS-mediated tumorigenicity, is a key metabolic manifestation associated with KRAS-mutant cancer cells." (PMID 35039048, 2022). "More than half of all KRAS-driven cancers are caused by the three most common KRAS alleles, G12D, G12V, and G12C, which account for approximately 100,000 new cases in the United States." (PMID 35573474, 2022).
cancer (continued). "These abilities conferred by KRAS mutations constitute an obstacle to anti-cancer therapies, leading to intensive efforts to develop new strategies to directly or indirectly target KRAS." (PMID 35883626, 2022). "Although the KRAS protein is closely associated with cancer, recent studies have shown that the KRAS protein can cause oncogenic mutations around activation sites (e.g., G12C, G12D, etc.), leading to downstream RAFs and overexpression of PI3K proteins." (PMID 35631410, 2022). "KRAS is the most frequently mutated oncoprotein in human cancers, affecting 25% to 30% of patients with NSCLC." (PMID 36483040, 2022). "This gradual progression towards invasive cancer is supported by a unique dependency on the mutated KRAS oncogene, prevalent in more than 90% of PDAC patients." (PMID 35800049, 2022). "We established a substantial association between the KRAS level and OS in six types of cancer using PrognoScan, which collects data mainly from the Gene Expression Omnibus database." (PMID 35563733, 2022). "GLANT6 mRNA expression showed no strong correlation with other GALNTs or mucins but was significantly higher in KRAS mutated or BRAF wild-type early-stage cancers." (PMID 35692787, 2022). "KRAS is a member of the Ras family, which is a common protooncogene with a mutation rate of up to 30%, and is associated with a variety of cancers with poor prognoses." (PMID 36164371, 2022). "They found that patients with HGD or cancer exhibited higher numbers and concentration of mutations other than KRAS/GNAS (also a higher overall mutation concentration) in their pancreatic juice." (PMID 35053560, 2022). "While a vast amount of genetic data is available for the cancer-associated KRAS gene, how KRAS is controlled at the post-transcriptional level is not well understood." (PMID 35546148, 2022). "KRAS is one of the most highly mutated oncoproteins, which is overexpressed in various human cancers and implicated in poor survival." (PMID 36224201, 2022). "Overall, we conclude that PTX3 is expressed in PDAC tissues, and is produced by stromal and cancer cells, likely in response to an associated inflammation that characterizes KRAS-harboring tumors, or in response to local tissue damage." (PMID 35681634, 2022). "Research on direct inhibition of KRAS mutations date back to the discovery of RAS-activated mutations in human cancer cells in the 1980s when RAS-activated mutations were found in human cancer cells." (PMID 35922812, 2022). "This was also evident in KRAS mutation-driven cancers such as NSCLC and pancreatic ductal adenocarcinoma (PDAC)." (PMID 36139366, 2022). "The distribution of mutated KRAS codons (left) was distinct from that observed in a pan-cancer assessment." (PMID 35768438, 2022). "The G13D and G12V mutations account for 13% and 24% of KRAS mutations across all human cancers, respectively." (PMID 35879364, 2022). "KRAS is the most mutated proto-oncogene that has been identified in cancer, and treatment of patients with KRAS mutations remains an arduous challenge." (PMID 35862868, 2022). "In our study, high expression of both KRT15 and KRT19 in low-risk ERG fusion negative patients was associated with the enrichment of common cancer-associated gene signatures, especially KRAS." (PMID 36033462, 2022). "Known as the ‘holy grail’ of targeted cancer therapies, KRAS is the most frequently mutated oncogene in human malignancies." (PMID 36284306, 2022). "The recent establishment of differential effects on metabolism of the two KRAS splice variants suggest the possibility of exploiting therapeutically unique metabolic vulnerabilities in cancers with relatively high expression of the KRAS4A." (PMID 36393833, 2022). "With the exception of CDKN2A, which carried few mutations overall, all genes carried high levels of cancer driver mutations ranging from 40% in ARID1A to 85% in KRAS." (PMID 36311816, 2022).
cancer (continued). "KRAS is the oncogene most frequently mutated in cancer and features in the group of key cancer targets." (PMID 36010567, 2022). "Glycine 12 mutations in KRAS, which result in the constitutive activation of the small GTPase, are among the most frequent mutations in colorectal and other cancers." (PMID 36005292, 2022). "In this section, we describe recent advances in the development of therapies targeting KRAS mutation cancers, including directly targeting KRAS itself and RAS effector pathways, namely MAPK and PI3K." (PMID 35922812, 2022). "In HEK293T cells, the cancer causing tylotic iRhom2 mutant D188N enhanced amphiregulin release by oncogenic KRAS mutations." (PMID 35971826, 2022). "KRAS in human genome acts as a proto-oncogene whose mutations are implicated in several malignancies, about 20% in all human cancers, including lung adenocarcinoma, ductal carcinoma of the pancreas, and colorectal cancer." (PMID 36012138, 2022). "This review will therefore summarize the current state-of-the-art of the clinical relevance of KRAS mutations as well as the most recent advances in KRAS-targeted anti-cancer strategies, focusing in particular in lung AC." (PMID 36077640, 2022). "Cancer cells transfer KRAS mutations through exosomes to neutrophils and induce neutrophil recruitment and NETosis via upregulation of IL8, promoting cancer cell proliferation." (PMID 35574410, 2022). "Cancer cells carrying oncogenic mutations in KRAS or PTEN induce macropinocytosis, thereby allowing them to survive and proliferate under conditions in which amino acids are limiting." (PMID 35287706, 2022). "CMS3 or metabolic tumors comprise 13% of cases and have frequent KRAS mutations and dysregulation of cancer metabolic pathways." (PMID 36530921, 2022). "RAS is one of the most frequent mutations in human cancer and KRAS is the most frequently mutated isoforms, constituting approximately 86% of all RAS mutations." (PMID 36145516, 2022). "Gain-of-function missense mutations in KRAS account for the majority of RAS gene mutations in human cancer (75%)." (PMID 35045886, 2022). "Three RAS genes, HRAS, NRAS, and KRAS, are the most frequently mutated oncogenes in cancer, with the most paramount mutation being the KRAS mutation." (PMID 35281897, 2022). "While each Ras member is involved in cancer, KRAS is surely the major cancer-causing isoform, accounting for 75% of all Ras-associated tumors." (PMID 35890348, 2022). "Mutations in KRAS gene lead to oncogenic conversion ensuing in constitutive activation of downstream signal transduction cascades and thus cancer development and progression as well as specific drug sensitivity." (PMID 36386815, 2022). "Lysine deacetylases (KDAC) inhibition suppresses cancer growth in mutated adenocarcinoma cells overexpressing amphiregulin via overcoming primary gefitinib resistant KRAS mutation." (PMID 35705962, 2022). "PI3K pathway mutations (26% vs. 8%) and homologous recombination DNA repair (HRR) defects (35% vs. 12.5%) were more common among KRAS G12R vs. non-G12R mutated cancers." (PMID 36124727, 2022). "Sotorasib (LumakrasTM) is indicated to treat non-small-cell lung cancer (NSCLC), and it targets a specific mutation in the KRAS protein, which is associated with the development of various forms of cancer." (PMID 35164339, 2022). "Most notably, multiple HLA-C*08:02-restricted TCRs specific for the oncogenic hotspot mutation KRAS-G12D were identified in several cancer patients." (PMID 35587797, 2022).
cancer (continued). "KRAS mutations have been found to facilitate tumorigenesis in approximately 30% of all human cancers and 23% of the endometrial hyperplasia and the endometrioid carcinoma." (PMID 35796805, 2022). "These efforts are critical for patients with KRAS G12D mutations, which make up a large subset of Ras-mutated cancers, especially for PDAC where the therapeutics currently available are providing meager benefits in the majority of cases." (PMID 36531078, 2022). "KRAS is the cancer gene with the most mutations in a single place and is the first to be identified to have a causal relationship with human cancer." (PMID 35631410, 2022). "Although KRAS is a proto-oncogene associated principally with cancer, at the transcriptional level it acts as a short-term inductor to astrocytes in response to stimulus and as a sensor that adapts cells to metabolic needs and oxidative stress in the brain." (PMID 35032285, 2022). "In our study, the frequency of KRAS mutation was 30.6%, which is consistent with the reported mutation rate of 15%-30% in cancer." (PMID 36447228, 2022). "WNT/β-catenin and KRAS signaling co-operate in cancer progression and are the leading cause of establishment of treatment resistance and poor patient outcomes." (PMID 35664781, 2022). "Oncogenic KRAS activation and cancer-associated fibroblasts have been shown to play an important role in generating an immunosuppressive microenvironment." (PMID 36212775, 2022). "Numerous attempts to develop targeted molecules against KRAS-mutated cancers have been unsuccessful due to KRAS protein picomolar affinity for the abundance of cellular guanosine triphosphate (GTP)." (PMID 35205778, 2022). "On the other hand, the subset of EGFR signaling in cancer was clearly over-represented in patients three and four, both showing mutated KRAS, and PIK3CA was also affected in the oldest patient (patient four)." (PMID 36005154, 2022). "The top 5 human cancers among these KRAS somatic mutations are pancreas (57%), large intestine (35%), biliary tract (28%), small intestine (17%) and lung (16%)." (PMID 35305624, 2022). "KRAS G12R vs. non-G12R mutated cancers contained significantly more co-mutations in the PI3K pathway (26.1% vs. 8.0%, P = .027), and more HRR gene defects (34.8% vs. 12.5%, P =.025)." (PMID 36124727, 2022). "KRAS has been regarded as an important drug target for cancer treatment and its conformational changes caused by ligand bindings and mutations are requisite for drug design." (PMID 35425180, 2022). "Globally, among the ~ 18 million new cancer diagnoses each year, ~ 2.6 million cancer patients are estimated to harbor a KRAS mutation (i.e., ~ 14% of all cancer cases)." (PMID 35045886, 2022). "Anti-EGFR monoclonal antibodies are ineffective in CRC patients with a KRAS mutation due to cancer’s genetic heterogeneity." (PMID 36005485, 2022). "i3 cancers had more frequent KRAS, PIK3CA and BRAF mutations, including mutations known to be associated with more prominent MAPK pathway upregulation." (PMID 35773407, 2022). "The oncogenic Ras isoforms, KRas, HRas and NRas, whose mutations have been found in more than 30% of human cancers, as well as overexpression of growth factors and mutations of their receptors in human cancer, all lead to the activation of this pathway." (PMID 35563547, 2022). "In cancer cells harboring a KRAS-activating mutation, TBK1 is observed to promote cancer cell survival and proliferation by activating both the NF-κB and mTOR1 pathways." (PMID 35395857, 2022).